CTLA4 (cytotoxic T-lymphocyte associated protein 4)
Diseases named in the same sentence as CTLA4 in open-access papers (continued):
Sharing a sentence is not in itself a finding about the gene and the disease.
breast carcinoma (continued). "One of them is demonstrated in an animal model blockage of CD73 leading to improved efficiency of anti-CTLA-4- or anti-PD1-induced antitumor activity in colon, prostate, and breast cancer subjects." (PMID 34440813, 2021). "We also found that serum ObR levels were positively correlated with serum CTLA-4 (p = 0.0056), TNF-α (p = 0.0025), PD-1 (p = 0.0023) levels as reported in breast cancer patients, and with serum PD-L1 levels (p = 0.0002)." (PMID 33644151, 2021). "The co-expression of CTLA-4 and CD80 was indeed observed in one TREG cluster in the breast cancer TME." (PMID 33467084, 2021). "The expression of Treg-related genes involving Treg-suppressive function was largely unchanged between CD177+ and CD177− TI Treg cells in human breast cancer or ccRCC, with slight elevation of ICOS, TIGIT, and CTLA4." (PMID 34599187, 2021). "Multiple ICRs, including PD-1, CTLA-4, TIM-3, and LAG-3, were found to be upregulated in breast cancer tissues as compared to normal breast tissue." (PMID 33823818, 2021). "The serum CTLA-4, TNF-α and IL-6 levels of 57 female cats with mammary carcinoma were determined by ELISA, and immunohistochemistry was performed to evaluate CTLA-4 and FoxP3 expression in tumor cells and interstitial lymphocytes." (PMID 32123292, 2020). "In this study, the expression patterns of immune checkpoints, such as PD-1, CTLA-4, TIGIT, and LAG3, are quite different from that of VISTA in breast cancer microenvironment." (PMID 33250890, 2020). "Materials and methods: We used the data from The Cancer Genome Atlas (TCGA) to analyze the expression of CTLA-4 in different types of breast cancer, and analyzed the TNBC data of CTLA-4 related co-expression genes by WGCNA and enrichment analysis." (PMID 33033520, 2020). "In a recent study, combining entinostat with anti-PD-1, anti-CTLA-4, or both significantly improved tumor-free survival in the HER-2/neu transgenic breast cancer mouse model." (PMID 32158754, 2020). "From these data, we found that most studies focused on the effect of CTLA4 and PD1/PDL1 checkpoint inhibitors on breast cancer, and only a small portion of patients responded to these treatments." (PMID 32602545, 2020). "High expression levels of CTLA-4 and TIGIT were correlated with favorable prognosis in breast cancer." (PMID 32602545, 2020). "Several clinical trials of immune checkpoint blockades focused on the effect of CTLA4 and PD1/PDL1 checkpoint inhibitors on breast cancer." (PMID 32602545, 2020). "Previously, we showed that the co-blockade of PD-1 and PD-L1 upregulated the surface expression of CTLA-4, TIM-3, and LAG-3 on CD4+ T cell subsets by using a co-culture system with human breast cancer cell lines." (PMID 32616706, 2020). "Expression of CTLA-4 was evaluated in tumor cells and infiltrating lymphocytes of TNBC paraffin-embedded biopsies, using an antibody that was previously validated in a breast cancer study." (PMID 32850353, 2020). "We determined the kinetics and level of expression of key inhibitory ICs (PD-1, CTLA-4, TIM-3 and LAG-3) and Treg-related markers (FoxP3 and Helios) in CD4+ T cells in the absence or presence of breast cancer cells." (PMID 31614877, 2019). "In mice bearing poorly immunogenic breast carcinoma, treatment with CTLA-4 blockade in combination with RT (vs. CTLA-4 blockade alone) resulted in decreased tumor growth and metastasis with improved survival." (PMID 30100909, 2018). "Around 77.4% of the clustered TCGA breast cancer patients’ evasion was through TGF-β1-mediated immunosuppression, 57.7% with DcR3, 48.0% with CTLA4, and 34.3% with PD-1." (PMID 30513096, 2018). "Our data demonstrate that both DNA and histone modifications are involved in upregulation of PD-1, CTLA-4, TIM-3, and LAG-3 in breast tumor tissue and these epigenetic modifications could be useful as diagnostic/prognostic biomarkers and/or therapeutic targets in breast cancer." (PMID 29983831, 2018).
breast carcinoma (continued). "We first examined the expression of CTLA-4 on breast cancer cell lines and screened out breast cancer cell line MDA-MB-231, which highly express CTLA-4 intracellularly and on cell surface." (PMID 28099147, 2017). "We have previously demonstrated that CTLA-4 is immune dysregulated in breast cancer and there is a significant increase of CTLA-4 expression not only by T cells from breast cancer patients but also by breast cancer cells themselves." (PMID 28099147, 2017). "Blockage of CTLA-4 via anti-CTLA-4- mAbs (e.g. ipilimumab and tremelimumab) is predicted to enhance T-cell activity against tumor cells and is under clinical trial for breast cancers (NCT02892734 and NCT02563925)." (PMID 29069872, 2017). "Currently, immune checkpoint therapies by targeting CTLA-4, PD-1, or lymphocyte activation gene-3 (LAG-3) pathways for breast cancer are still in clinical trial." (PMID 28085094, 2017). "In metastatic mammary tumors, the number of lung metastases was reduced in a CD8+-dependent fashion after 12 Gy followed by CTLA-4 blockade." (PMID 28791250, 2017). "Combination treatment of anti-CTLA4, radiation, and anti-OX40 using the ideal timing in a transplanted spontaneous mammary tumor model demonstrated tumor cures." (PMID 27281029, 2016). "Previous studies showed that SNPs of Cytotoxic T lymphocyte antigen -4 (CTLA-4) and B and T lymphocyte attenuator (BTLA) might confer susceptibility to breast cancer, which suggests the critical role of costimulatory molecules in the development of breast cancer." (PMID 21917182, 2011). "A single-institution study explored the safety and efficacy of brain radiotherapy and concurrent tremelimumab-mediated CTLA-4 blockade with or without trastuzumab for patients with breast cancer brain metastases." (PMID 40405250, 2025). "In HER2-positive breast cancer with APOBEC-enriched features, combining anti-CTLA-4 with anti-HER2 therapy may offer benefits." (PMID 40356722, 2025). "We show that a high tumor expression of the immune checkpoint gene CTLA4 is associated with an excellent prognosis and high TIL scores in patients with lymph node-negative, basal-like breast cancer in the Oslo1 study." (PMID 40523912, 2025). "Primary tumors from MMTV-PyMT mice, or resulting from E0771 breast cancer cell transplantation, did not respond to either programmed cell death protein 1 (PD-1) or cytotoxic T-lymphocyte antigen 4 (CTLA-4) inhibitors alone, or in combination with ALK1-Fc." (PMID 39808498, 2025). "In conclusion, the present study identifies high CTLA4 gene expression as a biomarker for excellent prognosis in patients with primary, lymph node-negative, basal-like breast cancer." (PMID 40523912, 2025). "Similarly, in breast cancer, A3 activity has been shown to enhance immune infiltration and induce antitumor adaptive immune responses, sensitizing HER2-driven tumors to anti-CTLA-4 checkpoint inhibition." (PMID 39764440, 2024). "Among different breast cancer subtypes, TNBC shows the highest expression of CTLA-4." (PMID 39741315, 2024). "In recent years, studies have reported that anti-CTLA-4 Ab administration can induce eosinophil accumulation and normalize blood vessels in breast cancer model mice." (PMID 39106430, 2024). "However, in breast cancer, young mouse models show a significantly better response to anti-PDL1 or anti-CTLA4 treatment compared to aged mouse models." (PMID 38972884, 2024). "In mammary tumor with BRCA mutation mice from GSE130472 dataset, both senescence signature of groups receiving anti-PD-1 and anti-CTLA4 therapies were lower than those of groups without immunotherapy." (PMID 38972884, 2024). "In recent years, ICIs have also made great progress in treating breast cancer, but there is no systematic summary of the application of CTLA-4 inhibitors in breast cancer." (PMID 37860188, 2023).
breast carcinoma (continued). "A significant increase in CTLA-4 expression was observed at cycle 17 in patients with both recurrent and non-recurrent breast cancer post-trastuzumab therapy (p-value<0.05)." (PMID 38406785, 2023). "Considering our previous results showing that cats with mammary carcinoma have higher circulating levels of several immunomodulatory molecules (IL-6, TNF-α, CTLA-4, PD-1, PD-L1, VEGF-A, VEGFR-1, VEGFR-2, and LAG-3), the serum TIM-3 levels were evaluated to check for statistical correlations." (PMID 36672332, 2023). "IT LSAM-DTX administered with systemic anti-CTLA-4 reduced primary breast cancer TV and reduced or eliminated metastatic spread without added systemic toxicity." (PMID 36058988, 2023). "Among BC subtypes, the phenotype of PD-L1+CD45−CK+ was present in 41% of TNBC and 29% of luminal patients, while the phenotype of CTLA-4+CD45−CK+ was present in 36% of TNBC and 23% of luminal patients, implying that immunosuppressive phenotypes potentially predominate in TN breast cancer." (PMID 37046635, 2023). "T‐cell checkpoint molecules (PD‐1 and CTLA‐4) were generally not expressed in cohort A which was the patient population with the longest interval to breast cancer relapse." (PMID 36751105, 2023). "In summary, this work demonstrated the improved therapeutic efficacy achieving durable complete responses in the immunologically cold 4T1 murine breast cancer model of a novel combination immuno-oncology regimen comprising of the triple combination of N1, FSL-1, and R848 combined with CTLA4 ICB." (PMID 37190294, 2023). "This study aimed to determine the correlation between CTLA-4 expression in peripheral blood and insulin-like growth factor-1 (IGF-1) serum levels and their impact on trastuzumab responsiveness in HER-2-positive patients with breast cancer." (PMID 38406785, 2023). "In addition to breast cancer, clinical trials of CTLA-4 inhibitors are being conducted in a variety of tumors and include bispecific antibodies against CTLA-4 and PD-1/PD-L1." (PMID 37860188, 2023). "As in the case of PD-1, the CTLA-4 molecule and its participation in the pathogenesis of neoplastic diseases, including EBV reactivation, is quite well documented in the literature, especially in gastric cancer, breast cancer, and epithelial cancers." (PMID 37835480, 2023). "Although CTLA-4 ranked third in terms of correlation with PIMREG, it only demonstrated a trend towards conventional positive correlation levels, and further studies on therapies targeting CTLA-4 in breast cancer are still necessary." (PMID 37483962, 2023). "Additionally, FOXP3 has a significant positive correlation with PDCD1, CD274, CTLA4 and TMB in breast cancer, and FOXP3 expression showed a statistically significant correlation with infiltration of immune cells." (PMID 35614183, 2022). "To further investigate the combined efficacy of targeting HIF-1α during anti–CTLA-4 therapy, we performed similar drug-treatment experiments using immunocompetent C57BL/6 recipients and the E0771 breast cancer or MC38 colon adenocarcinoma model and observed synergistic effects in all models." (PMID 35239514, 2022). "Moreover, the expression of LAG3, CTLA-4, PD-L1, CD274, TIGIT, HAVCR2 and PDCD1LG2 was upregulated in the TFRC high-expression group compared with the TFRC low-expression group in breast cancer." (PMID 35847985, 2022). "Anti-CTLA-4 drugs, such as ipilimumab and tremelimumab, have not been approved in the treatment of patients with breast cancer, but there are many ongoing trials investigating the therapeutic role of ipilimumab in breast cancer." (PMID 35015209, 2022). "Additionally, we found that FOXP3 had a significant positive correlation with PDCD1, CD274, CTLA4 and TMB in breast cancer." (PMID 35614183, 2022).
breast carcinoma (continued). "As a negative control, LDH release and cytokines secretion, following treatment with the immunomodulatory mAbs, were also measured when unfractionated hPBMCs or the two subpopulations were co-cultured with the breast cancer MCF-7 cell line, which is PD-L1-negative and expresses low levels of CTLA-4." (PMID 36358708, 2022). "Interestingly, high expression levels of CTLA-4 and TIGIT were correlated with favorable prognosis in breast cancer." (PMID 35646057, 2022). "In the present study, we have shown that blockage of CTLA-4 receptor on lymphocytes and concomitant reduction of CD4+CTLA-4+ and CD8+PD-1+ cells seem to be a crucial element in inhibition of MDA-MB-231 breast cancer cell proliferation and their arrest in the G1-phase." (PMID 34440813, 2021). "A recent study showed that anti-CTLA4 treatment in orthotopically implanted EO771 and spontaneous mouse mammary tumor virus (MMTV)-PyVT breast cancer murine models induced tumor vessel normalization and increased treatment efficacy, through eosinophil infiltration." (PMID 34572273, 2021). "As TNBC is more likely to respond to immunotherapy than other breast cancer subtypes, we found a group of TNBC patients who may respond to immune checkpoint inhibitors, especially TNBC patients with PD-1 and CTLA4 upregulation in the immune subtype." (PMID 34131286, 2021). "To date, the assessment of CTLA-4/ PD-1 inhibition on interactions between lymphocytes and different subtypes of breast cancer has not yet been thoroughly analyzed." (PMID 34440813, 2021). "Since PI3Kα is frequently mutated or activated in BCs, we chose to investigate the effects of alpelisib combined with PTX in response to ICI (anti-PD-1 and anti-CTLA-4) using a luminal, TNBC-like PyMT orthotopic implantation mouse model of breast cancer in C57BL/6 mice." (PMID 34069042, 2021). "Specific T cell clusters in the breast cancer TME of all subtypes show differential expression for predysfunctional markers (e.g., TCF7), "transitional markers" (e.g., GZMK, IL7R, and PD-1) and late dysfunctional markers (PD-1, CTLA-4, TIM3, and LAG3)." (PMID 33467084, 2021). "The results showed that the predictive scores had a significant positive correlation with the immune checkpoints, such as PD1, PD1L2, and was particularly highly correlated with CTLA4, LAG3, and IDO1, suggesting immune regulation plays a key role in the prognosis of breast cancer chemotherapy." (PMID 34526986, 2021). "Considering the lack of knowledge, feline serum VISTA levels from cats with mammary carcinoma were compared with healthy controls, and with serum levels of PD-1/PD-L1, CTLA-4, LAG-3, IL-6, and TNF-α." (PMID 34771722, 2021). "CTLA-4 and TIGIT were related to longer OS and RFS in breast cancer patients." (PMID 32602545, 2020). "It has also been reported that expression of CTLA-4 occurs in around 50% of breast carcinomas, but not in normal breast tissues." (PMID 32850353, 2020). "Using data from TCGA database and GEO database to analyze the expression of CTLA-4 among different molecular subtypes, we concluded that the expression of CTLA-4 in TNBC was significantly higher than that in other molecular subtypes of breast cancer." (PMID 33033520, 2020). "CTLA-4 and TIGIT were correlated with better prognosis in breast cancer." (PMID 32602545, 2020). "Although feline mammary carcinoma is increasingly recognized as a valuable cancer model, no studies on CTLA-4 function had been conducted in this species." (PMID 32123292, 2020). "Consistent with the non-responsive nature of luminal B breast cancers to ICB, we found in our study that anti-PD1 in combination with anti-CTLA4 had no discernable therapeutic benefit in wildtype or FIP200 KI PyMT mammary tumors." (PMID 32743346, 2020). "A study of standard-of-care brain radiation with tremelimumab-mediated CTLA4 blockade for women with breast cancer brain metastases conferred non-CNS disease control in 10% (2/20) of women with HER2-normal disease." (PMID 29881518, 2018).
breast carcinoma (continued). "Using the poorly immunogenic murine 4T1 mammary carcinoma model, this study showed that only combinatory treatment of radiation and CTLA-4 inhibition, but not either treatment alone, exhibited significant survival advantage over control." (PMID 30558196, 2018). "The mechanisms leading to the apparent lack of anti-CTLA-4 activity when administered as a monotherapy in certain solid tumors, including breast cancer, are still not well understood." (PMID 30185216, 2018). "This study shows a significant overexpression of CTLA-4 in >50% of breast carcinomas with no such overexpression of CTLA-4 in benign breast tissues." (PMID 29672601, 2018). "In this study, anti-CTLA4 therapy was not able to synergize with high dose radiation to induce an abscopal effect in the TSA mouse mammary carcinoma model." (PMID 29556198, 2018). "In fact, anti-CTLA-4 monotherapies have shown no or very limited therapeutic advantage against breast cancer when administered alone, although their efficacy has been improved by combination with other agents, which opens the field to new investigations." (PMID 30185216, 2018). "In contrast to the anti-PD-1-based therapies and in line with previous reports on breast cancer, anti-CTLA-4 monotherapy did not result in a therapeutic benefit in MC1 PDXs." (PMID 30185216, 2018). "A preclinical trial that examined the combination of an MMP inhibitor and anti-CTLA4 antibodies in mice with breast cancer displayed delayed tumor growth and metastases reductions in mice treated with MMP inhibitor verses those treated with anti-CTLA4 antibody alone." (PMID 28919894, 2017). "To identify the mechanisms by which tumour-directed radiation synergizes with anti-CTLA4 antibody (anti-CTLA4) to induce anti-tumour T cells against poorly immunogenic tumours, we used TSA, a mouse mammary carcinoma refractory to immune checkpoint inhibitors, as a model." (PMID 28598415, 2017). "Animals treated with anti-CTLA-4 mAb and anti-OX40 mAb and vaccinated with anti-DEC-205 (dendritic and epithelial cells, 205 kDa)-HER2 (human epidermal growth factor receptor 2) had significantly improved survival in a mammary carcinoma model." (PMID 27827885, 2016). "An RT-PCR study of four breast cancer cell lines showed extracellular transcripts of CTLA-4 to be present in all four cell lines, but not the full-length form of CTLA-4." (PMID 25893809, 2015). "A recent study has documented enhanced FOXP3 and CTLA-4 transcripts in BMCs in breast cancer, but did not assess effect of NAC or surgery." (PMID 23320561, 2013). "Multicolor immunophenotyping was used to determine the expression of PD‐1, TIM‐3, LAG3, CTLA‐4, CCR7, CD45RO, CD127, CD25, CXCR5, and ICOS molecules on CD3+CD4−CD56−CD8+ cytotoxic T cells freshly obtained from the lymph nodes and the peripheral blood samples of the breast cancer patients." (PMID 38069525, 2023). "In the present study, MYL5 expression negatively correlated with the markers of T cells exhaustion, such as PDCD1 (PD-1), CD274 (PD-L1), and CTLA4 (cytotoxic T-lymphocyte antigen 4), which indicated that MYL5 could play a positive role in prolonging survival prognosis for breast cancer patients." (PMID 36846347, 2023). "However, the potential interplay between A2AR and PD-1 or CTLA-4 has not yet been elucidated in human breast cancer." (PMID 37753093, 2023). "In addition, SLC31A1 was positively related to the expressions of immune checkpoints CD274 and CTLA4, suggesting that targeting SLC31A1 might be a potential way to improve immunotherapy efficacy in breast cancer." (PMID 37884650, 2023). "In breast cancer, atezolizumab, a PD-L1 antibody with ADCC activity against PD-L1 positive TNBC was shown to be effective, while malignant pleural mesothelioma achieved better treatment outcomes when treated using a combination of anti CTLA-4 and PD-1 antibodies." (PMID 36698400, 2022).